MIR4319 (microRNA 4319)
Synonyms: hsa-mir-4319
Gene: MicroRNA gene on chromosome 18 (44,970,082 to 44,970,166, reverse strand). Ensembl gene ENSG00000265957.
Homologues: Orthologues: chimpanzee MIR4319 (100% identical).
Diseases named in the same sentence as MIR4319 in open-access papers:
MIR4319 is named in the same sentence as 1 disease in open-access papers, as found by Europe PMC text mining. Sharing a sentence is not in itself a finding about the gene and the disease. The quoted sentences say what the papers report.
non-small cell lung carcinoma (1 paper, 2021). A group of at least three distinct histological types of lung cancer, including non-small cell squamous cell carcinoma, adenocarcinoma, and large cell carcinoma. "For example, expression of lncRNA GNAS antisense 1 (GNAS-AS1) in non-small cell lung cancer (NSCLC) and BC, enhances M2 macrophage polarization and consequently tumor immune-evasion through regulation of GNAS-AS1/MIR4319/NECAB3 and GNAS-AS1/miR-433-3p/GATA3 axes, respectively." (PMID 34943820, 2021).